LOX (lysyl oxidase)
Diseases named in the same sentence as LOX in open-access papers (continued):
Sharing a sentence is not in itself a finding about the gene and the disease.
tumor (continued). "CAFs produce collagen crosslinking enzymes of the lysyl oxidase (LOX) family, which increase the stiffness of the ECM and thereby affects the growth and invasion of tumor cells." (PMID 31159419, 2019). "The deposition of fibronectin (FN), MMPs, lysyl oxidase (LOX) and other factors remodeled the tissue microenvironment to facilitate tumor cell adhesion and colonization." (PMID 31796058, 2019). "This suggests that LOX can upregulate the expression and enzyme activity of MMP-2 and MMP-9, which verified our results in human tumor tissues." (PMID 31777578, 2019). "Due to crosslinking collagen by lysyl oxidase (LOX), the ECM of the tumour becomes more stiff, leading to increased focal adhesions and enhanced PI3K signalling, thereby indirectly ensure tumour progression." (PMID 30302588, 2019). "Inflammation involves high ECM remodeling with large ECM protein deposition, which are crosslinked by increased levels of lysyl oxidase (LOX), contributing to solid stresses, tumor ECM stiffening, and drug resistance." (PMID 31572718, 2019). "LOX and LOXL4 participate in tumor microenvironment remodeling and the formation of pre-metastatic niches." (PMID 29728125, 2018). "Lysyl oxidase (LOX) is another extracellular protein involved in collagen cross-linking and remodeling of extracellular matrix and has been correlated with tumor progression." (PMID 30583585, 2018). "Factors that promote tumor development or progression, such as TNF-α, TGF-β, or HIF-1, can upregulate LOX." (PMID 29732010, 2018). "LOX and LOXL2 as primary tumor-derived soluble factors contribute to formation of pre-metastatic niches in distant target organs." (PMID 29728125, 2018). "In these groups several noteworthy changes include the ECM cross-linking proteins, lysyl oxidase, lysyl oxidase-like 1, and tissue transglutaminase II (TGM2), which have been previously shown to play a role in tumor stiffness and progression." (PMID 30154546, 2018). "In addition, LOX/LOX-l inhibitors could be an important target to control these types of tumour." (PMID 30406137, 2018). "LOX/LOXL2 overexpression in human clear cell renal cell carcinoma (ccRCC) promoted tumor cell migration and adhesion, as well as matrix stiffness to enhance tumor progression and metastasis." (PMID 29732010, 2018). "Lysyl Oxidase Like 2 (LOXL2), one of the lysyl oxidase (LOX) family members and a matrix remodeling enzyme, promotes ECM remodeling, triggers EMT program and contributes to tumor progression and metastases." (PMID 30456206, 2018). "On the contrary, the secreted LOX mature enzyme is typically reported to increase ECM stiffness, activate oncogenic signalling pathways and play a tumour promoting role." (PMID 28947950, 2017). "By contrast, LOX gene expression was unchanged, whereas the LOX protein level was decreased in IPF lung, highlighting differential LO family expression in IPF lung tissue, which is similar to that reported during tumour progression and metastasis." (PMID 29125826, 2017). "We describe a pharmacological inhibitor of LOX, CCT365623, which disrupts EGFR cell surface retention and delays the growth of primary and metastatic tumour cells in vivo." (PMID 28416796, 2017). "Secreted LOX is reported to cross-link the ECM at distal sites to create pre-metastatic niches to which bone marrow-derived and tumour cells are recruited, facilitating the metastatic spread of cancer." (PMID 28416796, 2017). "LOX-mediated ECM cross-linking and stiffening induce integrin-mediated focal adhesion formation and PI3K signaling, promoting tumor growth and invasion." (PMID 28425924, 2017). "We show that pharmaceutical inhibition of LOX disrupts this signalling pathway, reducing EGFR signalling and delaying tumour progression." (PMID 28416796, 2017). "The role of the LOX family in cancer is unclear, and the data available (dealing particularly with LOX and LOXL24) suggest that these enzymes have both tumour-suppressing and tumour-promoting effects." (PMID 26804196, 2016).
tumor (continued). "Further, the combination of HIF, LOX, and VEGF not only enhances tumor cell proliferation, but also induces angiogenesis to induce the cells to serve a metastasis path." (PMID 28036074, 2016). "Inhibition of LOX enzymes, using Beta-aminopropionitrile (BAPN), initiated before implantation of AT-1 cells, reduced tumour growth." (PMID 26804196, 2016). "A stimulatory effect of LOX on tumour establishment and growth could be particularly important early after tumour cell injection when few cells have to interact successfully with a potentially hostile collagen rich environment but perhaps less important for established tumours facing less collagen." (PMID 26804196, 2016). "Thus, remodelling of the ECM by all of the LOX enzymes, by cross-linking collagen, might prepare the tumour-adjacent normal prostate tissue for tumour expansion and invasion or as suggested also be part of a defence mechanism induced to repair and strengthen the normal tissue." (PMID 26804196, 2016). "LOX and HIF-1α overexpression were observed in hypoxic EOC cells, with expression levels correlating significantly with metastasis and tumor stage in EOC." (PMID 26579497, 2015). "LOX IR in TINT epithelium was positively correlated to pEGFR and pAKT both in tumor and TINT epithelium." (PMID 26501565, 2015). "The extracellular matrix remodelling protein lysyl oxidase was found to be highly elevated in Kras/Lkb1 GEMMs and inhibition of lysyl oxidase with BAPN also impaired tumour progression." (PMID 26196184, 2015). "Our prediction was that in this context, LOX inhibition was likely to have more of an impact, as PDAC is well known to be a highly desmoplastic tumor with marked levels of stromal collagen." (PMID 26077591, 2015). "This would strongly support further development of LOX inhibitors for PDAC and the continued investigation of other approaches to target the tumor microenvironment in this disease." (PMID 26077591, 2015). "Since LOX is proteolytically processed into a fragment containing the lysyl oxidase enzymatic activity and an N-terminal propeptide (LOX-PP), experiments were conducted to determine in which of these fragments resided the tumor suppressor activity." (PMID 26258070, 2015). "LOX is involved in the hypoxic upregulation of HIF1A, and LOX and HIF-1α potentiate each other to foster tumor progression in the colon through the PI3K-Akt signaling pathway." (PMID 25790191, 2015). "Those genes reportedly involved in tumor cell adhesion, gap junction and ECM, such as CHD1, Cx26, Cx43, Cx45, COL1A1, FN1, LOX, ITGB1 and LAMA4, were also up-regulated following 3D cultures." (PMID 26055407, 2015). "The results indicated that lysyl oxidase catalyzed ECM-crosslinking impedes tumor drug diffusion, thereby forming a physical barrier that protects tumor cells from exposure to the systemically applied drugs." (PMID 26620400, 2015). "In other breast cancer cells driven by Her-2/neu (ERBB2), LOX-PP expression suppressed AKT, ERK, and NFκB activation, as well as cell migration, growth in soft agar and tumor formation in nude mice." (PMID 26258070, 2015). "In more aggressive and poorly differentiated tumors, LOX also induces epithelial–mesenchymal transition (EMT) and promotes metastatic dissemination by facilitating tumor cells invasion into vascular system (intravasation)." (PMID 24338768, 2014). "The same applies to the family of lysyl oxidase (LOX) enzymes and transglutaminases that also represent central molecules in regulating ECM organization and tumour progression." (PMID 26056582, 2014). "To evaluate NNK effects on the expression of lysyl oxidase (LOX), a tumor suppressor, we examined this enzyme at various levels in NNK-treated rat fetal lung fibroblasts (RFL6)." (PMID 25546273, 2014). "The active HIF will mediate activation of multiple genes involved in angiogenesis (e.g., VEGF), cell survival (e.g., IGF-1), and metastasis (e.g., LOX and PAI-1) and this drives tumour progression." (PMID 23690850, 2013).
tumor (continued). "We showed that the LOX-HIF-1α mutual regulation mechanism activates the AKT pathway and thus promotes tumor cells migration." (PMID 23545606, 2013). "A strong positive correlation between regional CA9, LOX and GLUT1 mRNA transcript levels and FAZA retention was revealed in a human tumor model suggesting that these genes display high hypoxia-specificity in vivo and are superior to LDH and GAPDH." (PMID 21306648, 2011). "Inhibition of HIF-1α, CAIX, LOX, or CXCR4 to reduce the development and growth of tumour metastases represent rational therapeutic strategies to disrupt the metastatic process." (PMID 22128892, 2011). "Alterations in expression levels of genes, such as LOX, ATP5L, GALNT3, and MME revealed by large-scale sequencing were confirmed between cell lines as well as in tumor specimens with different ERBB2 backgrounds." (PMID 21731642, 2011). "Because of this unexpected tumor-type dependent difference in expression pattern of LOX, the results in SCCVII tumors were confirmed with an independent assay for LOX, which align in a different region of the transcript." (PMID 21306648, 2011). "More specifically, normal cells adjacent to thetumour (Norm) were characterized by a lower expression of the tumour suppressorgene LOX, the receptors for interleukin 1(IL1R) and TGFβ(TGFBR) and by a higher expression of the pro-tumour genesCYR61 and CX3CL1." (PMID 21479216, 2011). "Cancer-relevant genes on 5q include the LOX gene, which has been shown to play an essential role in hypoxia-induced metastasis, the later is triggered by the disrupted VHL gene in the tumor cells." (PMID 20671976, 2010). "Our results suggest that LOX inhibition, perhaps by diminishing FAK activity, is able to suppress tumor cell-endothelial adhesion and/or extravasation." (PMID 19440335, 2009). "Since catalytically active LOX, whose levels could plausibly differ between vascular beds, may be able to act as a chemoattractant and a modulator of adhesion and the invasiveness of tumor cells, we investigated whether BAPN administration would alter the anatomical pattern of metastases." (PMID 19440335, 2009). "Additionally, novel oral aminomethy-lthiophene-based compounds, acting as dual LOX/LOXL2 inhibitors, have emerged as promising candidates due to their excellent bioavailability and anti-tumor activity." (PMID 41362727, 2026). "By utilizing engineered bacteria with nlpI gene deletion to enhance outer membrane vesicles (OMVs) biogenesis and introducing a bifunctional surface display system (INP-HlpA for tumor targeting and ClyA-EGFP for tracking), ENHL delivers lactate oxidase (LOx) to neutralize acidic stress." (PMID 41486457, 2026). "Furthermore, collagen crosslinking in the TME can increase under the influence of enzymes such as LOX, which leads to a stiffer ECM that facilitates tumor invasion and metastasis." (PMID 40721833, 2025). "Furthermore, recent research has shown that LOXs, including LOX and LOXL1–4, are crucial for tumour metastasis." (PMID 40786111, 2025). "Collagen Type I Alpha 1 Chain (COL1A1) and Lysyl Oxidase (LOX) were included as they were upregulated across the three solid stress compression and are important in modulating the tumour microenvironment as well as promoting cancer migration." (PMID 40371393, 2025). "The findings indicated a reduction in the fluorescence area fraction and mean fluorescence intensity of LOX and LOXL2 in the tumour region of individuals showing sensitivity to neoadjuvant chemotherapy compared to those exhibiting resistance, although statistical significance was not achieved." (PMID 40179101, 2025). "For example, inhibiting lysyl oxidase (LOX) family enzymes, which are involved in the crosslinking of ECM proteins collagen and elastin, can reduce matrix stiffness and improve drug delivery to tumor cells." (PMID 40076613, 2025).
tumor (continued). "In addition to integrins, small molecule inhibitors also target ECM‐modifying enzymes, such as LOX, which catalyzes the cross‐linking of collagen and elastin, thereby increasing ECM stiffness—a critical factor in tumor metastasis and fibrosis." (PMID 40686923, 2025). "There is growing evidence that the elevation of LOX levels serves as a prediction indicator for HCC and highlights the crucial function of LOX family members in HCC pathogenesis and the modulation of the tumour microenvironment (TME)." (PMID 40433591, 2025). "The peptides decreased the extracellular LOX activity in the human umbilical vein endothelial cells conditioned culture, but no in vitro or in vivo tumor trials were conducted." (PMID 40211368, 2025). "CSCs form the primary tumor can favor the diffusion of pro-tumorigenic and proangiogenic factors such as VEGF-A, TGFB1, TNF-alpha and lysyl oxidase (LOX) that induce the expression of S100A (a Ca2+ binding protein involved in endothelial remodeling) in the metastatic area." (PMID 39981232, 2025). "LOX and LOXL2 are genes upregulated by hypoxia, promoting tumour cell invasion and metastasis." (PMID 40179101, 2025). "Furthermore, extracellular matrix remodeling involves not only collagen accumulation, but also matrix metalloproteinases (MMPs) and lysyl oxidase (LOX), which alter the biochemical and mechanical properties of the TME, fostering an aggressive tumor phenotype." (PMID 40136347, 2025). "PDAC expression of LOX can enhance collagen crosslinking and the ECM protein SPARC can alter collagen trafficking to weaken basement membrane barriers, creating channels for tumor cell migration." (PMID 40662361, 2025). "LOX can affect VEGF induction, HIF-1α activation, and other mechanisms, playing an important role in the occurrence, development, invasion, and metastasis of various tumor." (PMID 39132501, 2024). "Lysyloxidase (LOX) highly expressed in CAFs can remodel the matrix collagen microenvironment, enhance matrix stiffness, and accumulate nuclear β-catenin giving rise to EMT and tumor invasion through the FAK phosphorylation pathway." (PMID 39744628, 2024). "To assess changes in mechanical compression in response to pan-LOX inhibition, we measured IP prior to explant using a pressure catheter probe in URCCA4.3 tumor-bearing mice following 4 weeks of treatment with vehicle, PXS-5505, and FOX with or without PXS-5505." (PMID 39101793, 2024). "The importance of LOX in remodeling the ECM to facilitate cancer cell metastasis has also been studied using CPMs and other seminal hybrid ABM-continuum frameworks that describe tumor growth within the microenvironment." (PMID 38495620, 2024). "(iv) Consequently, P-BS-CM1 → P-CM2 substantially regressed pulmonary PMN hallmarks like LOX accumulation, BMDC recruitment, S100A8 secretion, and E-cadherin expression to levels close to healthy tumor-free mice, whereas free BS and P-BS had limited effects." (PMID 38553476, 2024). "Dual targeting macrophages and microglia via inhibition of LOX and the CLOCK-OLFML3 axis generates potent antitumor effects and offers a complete tumor regression in more than 60% of animals when combined with anti-PD1 therapy in PTEN-deficient GBM mouse models." (PMID 39352749, 2024). "Here, we provide evidence that, in addition to already known factors such as PDGF and LOX, ADAM12 and rsBSG modulate the extracellular matrix as evidenced by the increased deposits of type 5 collagen in the stroma around the MCF7 tumor, producing increased ADAM12 in a nude mice tumor model system." (PMID 38892056, 2024). "In addition, lab work will identify biomarkers specific for a broader spectrum of cells like LOX, LOXL2, and MAPK15 to reveal cells with invasive phenotypes in the primary tumor and circulation." (PMID 39329988, 2024).
tumor (continued). "Although our previous studies have shown that LOX and CLOCK inhibition reduces tumor angiogenesis in GBM, further studies are needed to evaluate whether these treatments affect vascular architecture and vessel leakage in GBM tumors." (PMID 39352749, 2024). "An unbalanced increase in LOX expression and activity promotes an increase in ECM stiffness that induces mechanical activation of latent TGFβ and fuels the initiation of a vicious cycle that maintains an inflammatory environment and promotes tumor progression." (PMID 39015505, 2024). "The tumor-originated extracellular vesicles are responsible for the extracellular matrix (ECM) remodeling via the accumulation of fibronectin and the promotion of crosslinking by the ECM-modifying enzyme lysyl oxidase (LOX)." (PMID 37842237, 2023). "This evidence implies that tumor hypoxia and cell death are connected not only to ECM deposition in general, but also to fibronectin deposition specifically, which can also be explained by LOX overexpression." (PMID 37190331, 2023). "Treatment of A375 tumour-bearing mice with the lysyl oxidase inhibitor βAPN did not result in a reduction of radiotracer uptake in the tumour." (PMID 37565736, 2023). "Furthermore, we demonstrated that overexpression of Hic-5 using an adenovirus vector in human normal fibroblasts increased the expression of lysyl oxidase (LOX) that increases ECM stiffness and enhances tumor progression." (PMID 37156857, 2023). "The incremental process of bone metastasis development is initiated by establishing a premetastatic niche at distant organs created by several tumor-derived factors (CCL2, IL6, lysyl oxidase (LOX), and Dickkopf WNT signaling pathway inhibitor 1 (DKK1)) of the primary tumor." (PMID 37296869, 2023). "Moreover, the hypoxic microenvironment induces the production of lysyl oxidase (LOX), thereby promoting tumor cell invasion and facilitating their migration and metastasis." (PMID 37895467, 2023). "LOX and HIF-1 synergistically promote tumor proliferation and metastasis." (PMID 36293126, 2022). "In the hypoxic TME, the HIF-1α-mediated transcriptional upregulation of LOX not only increases the expression of ITG-α5 and its ligand fibronectin in tumor cells, but also induces collagen crosslinking and fibronectin assembly, forming the mechanical barrier to prevent drug transport." (PMID 36293126, 2022). "Unlike catalytically active LOX, LOX-PP exhibits tumor-suppressive functions in desmoplastic tumor contexts." (PMID 35804902, 2022). "Moreover, LOX can also promote the synthesis of HIF-1α protein by positive feedback, and the two factors synergize and regulate each other to promote tumor progression." (PMID 36419894, 2022). "Thus, the efficacy of combination LOX/immune checkpoint inhibition on PDAC metastasis, as well as on primary tumor growth in other desmoplastic tumor contexts, represents an important avenue for further study." (PMID 35804902, 2022). "LOX expression increases extracellular matrix stiffness and this, in turn, also enhances the expression of VEGF, as well as platelet-derived growth factor (PDGF) by tumor resident cells." (PMID 35682926, 2022). "This family comprises five cooper-dependent amine oxidases (LOX, LOXL1, LOXL2, LOXL3, and LOXL4), which are involved in several hallmarks of cancers, such as tumor microenvironment remodeling, invasion/migration, growth, inflammatory response, genomic stability, and resistance to chemotherapy." (PMID 36076905, 2022). "For glioblastoma cells that did not express PTEN, LOX was noticeably reduced and macrophage infiltration and tumor progression took place." (PMID 34687436, 2022). "Of note, in this system, tumor-derived or locally produced LOX are absent because MCF7 cells marginally express LOX." (PMID 34666995, 2022). "Importantly, the expression of COL1A2, LOX and LTBP2 significantly correlated with high tumor stage, with LOX and LTBP2 further impacting patient overall survival." (PMID 35340765, 2022).